HIF1A (hypoxia inducible factor 1 subunit alpha)
Diseases named in the same sentence as HIF1A in open-access papers (continued):
Sharing a sentence is not in itself a finding about the gene and the disease.
tumor (continued). "In addition, several studies have indicated that propofol may decrease the expression of HIF-1α and prevent tumor growth." (PMID 36463276, 2022). "Moreover, HIF-1α inhibition together with anti–PD-1 therapy could impair tumor growth in vitro and in vivo." (PMID 36032082, 2022). "The von Hippel–Lindau protein is a tumor suppressor gene involved in the negative regulation of HIF-1α in normoxic conditions, whereas mutations on the VHL gene or hypoxic conditions prevent HIF-1α degradation, which promotes the expression of angiogenic and inflammatory mediators." (PMID 35563616, 2022). "In addition, vascular endothelial growth factor (VEGF) is up-regulated affected by HIF-1α, which could promote metastasis and immune escape by inducing tumor angiogenesis." (PMID 36212414, 2022). "Hypoxia-inducible factor-1α (HIF-1α) is a master transcriptional regulator of the adaptive response to hypoxia that plays an essential role in various metabolic activities, including embryonic vascularization, tumor angiogenesis and pathophysiology of ischemic disease." (PMID 35819532, 2022). "Furthermore, secreted tumor-derived succinate belongs to a novel class of cancer progression factors, inhibiting tumor-associated macrophage polarization and promoting tumorigenic signaling through PI3K/AKT and HIF1α." (PMID 35089096, 2022). "The inhibitory functions of checkpoints could be reversed by anti-angiogenic agents, as when VEGF is blocked, tumor blood vessels decrease and tumor tissue hypoxia is induced, which in turn activates hypoxia-inducible factor (HIF-1α), and promotes cytokine production to activate CD8+ T cells 43-45." (PMID 35813484, 2022). "Here, expressions of VEGF and CD34 in the transplanted tumor tissues after bevacizumab treatment were lower, but HIF-1α expression was significantly higher than those in the control group, suggesting that the anti-angiogenic property of bevacizumab may exacerbate the hypoxic condition in the TME." (PMID 36046821, 2022). "For instance, YTHDF1 is associated with HCC maintenance, where HIF-1α swells YTHDF1 transcription by mediating HIF-1α-binding site 1 (HBS1) and HBS3 site of HIF-1α interacting with the YTHDF1 promoter region under hypoxic conditions, which zooms autophagy-related tumor growth and metastasis." (PMID 35864970, 2022). "Most importantly, the antiangiogenic efficacy of ATMO‐21 toward orthotopic human GBM was first investigated carefully, indicating that B1L@SpAcDex‐ATMO‐21 NPs could significantly inhibit the expression of tumor blood vessel‐related genes (HIF1α and VEGF) by upregulating PTEN expression." (PMID 34936240, 2022). "In the hypoxic condition, MUC1 promotes the recruitment of HIF-1α and p300 to the promoter region of glycolysis genes, upregulates the expression of glycolysis-related genes, increases glucose uptake and lactate production, and assists tumor cells to survive in hypoxic environments." (PMID 35879749, 2022). "Recent study showed that HIF1α was essential for tumor formation and HIF-1α regulates glycolysis 31, our data further supported the notion that KDM5C partially inhibited the elevated expression of HIF1α- and metabolism-related genes, which may be caused by loss of VHL." (PMID 34522206, 2021). "Therefore, the paracrine activity of PDGF-B and PDGF-D originating from intermediate/hypoxic middle-layer of GBM via canonical HIF1α stabilization may trigger the HIF1α stabilization in the GBM cells located in the oxygen-rich leading edge of the tumor." (PMID 34470658, 2021). "Therefore, how hypoxic environment and/or HIF-1α-induced transcriptional events lead to changes in NK cell metabolic processes and cytolytic function against tumor cells, within the tumor microenvironment, still remain unclear." (PMID 33920906, 2021). "But we have not detected whether HIF‐1α‐expressed fibroblasts interact with other immune cells, such as tumour‐associated macrophages, T cells, MDSC." (PMID 33943003, 2021).
tumor (continued). "Additionally, hypoxia stabilizes HIF-1α which may possess an antiapoptotic function, as tumor cells with elevated HIF-1α show higher resistance to apoptosis." (PMID 33796526, 2021). "Hypoxia may decrease tumor control through the induction of hypoxia-inducible factor 1α (HIF-1α)." (PMID 34034691, 2021). "Indeed, a specific knock-out of HIF-1α in macrophages decreases tumor aggressiveness." (PMID 34539584, 2021). "Therefore, HIF-1α plays several roles in the tumor, including regulation of angiogenesis in hypoxia, establishing and preserving the CSCs niche, promoting the stem cell phenotype, and increases the ability of self-renewal, proliferation, and tumorigenesis in CSCs." (PMID 34051847, 2021). "Similarly, Sorafenib treatment recruits tumor neutrophil infiltration in animal models as well as HCC patients by inducing the CXCL5 expression in tumor cells via the hypoxia-inducible factor 1-alpha (HIF1α)/nuclear factor-κB (NF-κB) pathway." (PMID 34830850, 2021). "In addition, it has been reported that targeted lactic acid metabolism can reduce the production of angiogenic factor (VEGF) by downregulating hypoxia-inducible factor 1a (HIF1a), which contributes to the normalization of tumor blood vessels and increases the infiltration of immune cells." (PMID 33859941, 2021). "Alternatively, the use of special microcarriers on the basis of liposomes or nanoparticles or dendrimers containing pharmacological inhibitors of HIF-1 or oligonucleotide vectors downregulating the HIF-1α expression may be an effectual way to suppress HIF-1 inside hypoxic tumor cells." (PMID 33806538, 2021). "Thus, APG is a powerful GC tumor therapeutic strategy of targeting hypoxia/HIF-1α." (PMID 34948250, 2021). "Hence, we wondered whether the decreased expression of HIF1α and HIF2α contributed to the increase in tumour volume and chemosensitization." (PMID 33986256, 2021). "Therefore, targeting HIF-1α-mediated metabolic pathways in tumor cells has been hypothesized to be a valuable therapeutic strategy." (PMID 33732648, 2021). "In addition, since HIF-1α is a transcription factor that facilitates both malignant and normal cell adaptation to hypoxic stress in the internal environment, it is particularly important to design drugs targeting only HIF-1α expressed in tumours to reduce the adverse effects." (PMID 35004308, 2021). "Several recent studies have described the expression of PD-L1 within tumor cells to be closely associated with accumulation of 2-deoxy-2-[fluorine-18] fluoro-D-glucose (18F-FDG) in positron emission tomography (PET), replacing hypoxia inducible factor 1α (HIF-1α) as an alternative marker." (PMID 33441183, 2021). "IHC for intrinsic hypoxia markers such as regulatory subunit of HIF-1, HIF-1α, and its downstream genes can also be used to assess tumor hypoxia; however, when applied for a small clinical biopsy sample, it may not reflect the hypoxic fraction of the entire tumor." (PMID 34747365, 2021). "We set sights on HIF‐1α, which has been widely reported that it can stably express only under hypoxic conditions and meanwhile activate the transcription of genes that were involved in tumour metabolism, cell proliferation and metastasis as a transcriptional factor." (PMID 33784010, 2021). "In addition, HIF1α inhibition was found to reduce PD-L1 expression in a mouse tumor model." (PMID 34575959, 2021). "Additionally, the tumor pharmacokinetic DCE-MRI perfusion parameters in patients with OC are negatively correlated with the expression level of HIF-1α, which can be used to screen the tumor characteristics of OC and help clinicians choose the best treatment options." (PMID 34659640, 2021). "Therefore, the regulatory function of USP14 on HIF1-α action revealed under hypoxia conditions in this work may also be applicable for the normoxic state in tumor cells." (PMID 34420039, 2021).
tumor (continued). "Additionally, this difference in outgrowth of disseminated tumor cells could be due to tumor cell-intrinsic properties driven by Hif1α expression or due to microenvironmental changes in the lung that result from Hif1α expression in the primary tumor." (PMID 34556788, 2021). "Tumor cells may produce reactive oxygen species (ROS), and these activate hypoxia-inducible factor 1 alpha (HIF-1α), nuclear factor kappa-B (NFκB), and consequent lactate production in the adjacent fibroblasts, which in turn is associated with faster growth of the cancer cells." (PMID 34778040, 2021). "However, whether and how HDACs involved in HIF-1α activation during hypoxia and influenced tumor progression in PC remain unclear." (PMID 34881179, 2021). "Moreover, CaO2-MNPs decreased the HIF-1α expression in tumor tissues of TNBC." (PMID 33546453, 2021). "Moreover, hypoxia and HIF1α are considered as an integral components of tumor microenvironment." (PMID 34068008, 2021). "Hence, we may hypothesize that HIF-1α-dependent chemoresistance occurs both in hypoxic tumor areas and in well-oxygenated ones characterized by a hypoxia-independent activation of HIF-1α." (PMID 33423689, 2021). "Moreover, high HIF-1α expression has been demonstrated in various tumours." (PMID 34256803, 2021). "For example, evidence has shown that HIF-1α/LDH-A mediates cell metabolism by causing a shift between aerobic glycolysis and oxidative phosphorylation, which alters PD-L1 expression; thus, the upregulated expression of checkpoint inhibitor PD-L1 induces tumor resistance to therapy." (PMID 34235071, 2021). "Thus, it seems that the VANGL1 gene may interact with VEGF-A and HIF1A signaling and enhance tumor malignancy." (PMID 33672900, 2021). "Here, we present evidence that pre-activation and subsequent HIF-1α-dependent metabolic shift of NK cells from oxidative phosphorylation into glycolysis are keys to overcome hypoxia-mediated impairment in NK cell survival, proliferation, and tumor cytotoxicity." (PMID 33920906, 2021). "Also, hypoxia/HIF1α exerts a tumor-promoting role by immunosuppression." (PMID 34686682, 2021). "However, the presented evidence provides better support to HIF-1α increasing tumour growth rather than causing cancer." (PMID 34154667, 2021). "GBM cells can undergo transitions in molecular subtype in response to chemotherapy or radiotherapy and according to the microenvironment of the tumor, which may lead to differences in effects between in vitro and in vivo experiments using HIF-1α and Smad3 inhibitors." (PMID 34707087, 2021). "As the tumor grows, there is a reduction in oxygen at the center of the tumor, creating adverse conditions of hypoxia, which induces increased expression of numerous pro-angiogenic factors, such as hypoxia-inducible factor 1-alpha (HIF-1α) and insulin-like growth factor type 1 receptor (IGF-1R)." (PMID 33419057, 2021). "Therefore, in tumors with HIF1 overexpression or overactivation, vitamin C treatment may increase the activity of HIF hydroxylases, with consequent HIF1α degradation and inhibition of the tumor promoting effects of this transcription factor." (PMID 33804775, 2021). "Moreover, anti-angiogenic therapy may lead to the onset of hypoxia, resulting in the activation of HIF1a in tumor cells with a consequence of tumor cell adaptation to hypoxia and the promotion of tumor angiogenesis." (PMID 34552922, 2021). "Moreover, an HIF-1α-dependent miR-210 upregulation has also been observed in myeloid-derived suppressor cells, significantly contributing to the malignant character conferred by hypoxic tumor microenvironment." (PMID 33934122, 2021). "HIF-1α has been identified to activate HIF-1β to form a transcription factor complex that regulates the expression of several genes, such as vascular endothelial growth factor and glucose transporters, which is strongly associated with angiogenesis and tumor growth." (PMID 34034691, 2021).
tumor (continued). "Researchers found that the expression of HE4 decreased after inhibition of HIF1-α expression or treated with HIF1-α inhibitor in tumor cells; HE4 could co-immunoprecipitate and co-locate with EGFR, and the interaction between HE4 and EGFR was enhanced after upregulation of HE4 expression." (PMID 35003362, 2021). "However, it also has been reported that tocilizumab could inhibit tumor growth through impairing tumor-related neovascularization and main proangiogenic factor VEGF-A and its transactivator HIF-1α in humanized breast orthotopic tumor xenografts." (PMID 33576874, 2021). "Those mice that received HPV-positive tumor cells showed a higher density of neo-blood vessels, which resulted in improved blood supply and thus less hypoxic tumor areas, which was paralleled by lower mRNA expression of hypoxia-responsive genes such as HIF-1α, GLUT-1 and VEGF-A." (PMID 34680369, 2021). "However, there have some researches about HIF‐1α transcriptional regulates tumor suppressor." (PMID 33463054, 2021). "Moreover, adaptability of tumor cells to hypoxia changes with regulation of HIF-1α and HIF-2α." (PMID 34307125, 2021). "We speculate that the efflux mechanism partly explains the unique TAC curve of the radiolabelled choline radiotracers in human tumours and, additionally, that HIF-1α accounts at least in part for the spatial heterogeneity of [18F]-D4-FCH PET, as previously reported." (PMID 34452207, 2021). "Thus, we could not determine whether the proliferative capacity of these disseminated tumor cells was altered by Hif1α expression prior to their development into histologically detectable lesions." (PMID 34556788, 2021). "Additionally, miRNAs can also regulate the tumour suppressors that negatively regulate HIF-1α." (PMID 34798868, 2021). "Besides, as the downstream molecule of PI3K/Akt, GSK3β participates in multiple signal pathways and its inactivation in hypoxia may contribute to angiogenesis and tumor growth by facilitating HIF-1α." (PMID 34329303, 2021). "Moreover, the most recent evidence has indicated that tumor-released succinate can activate succinate receptor 1 (SUCNR1) signaling to polarize TAMs toward tumor-supporting phenotypes through a SUCNR1-activated PI3K/HIF-1α axis." (PMID 34603327, 2021). "In this regard, it was suggested that tumor cells by promoting oxidative stress in CAFs could activate HIF-1α, which in turn promoted autophagy and glycolysis through the hypoxia-mediated degradation of CAV1 and enhanced either glucose transporters or glycolytic enzymes." (PMID 34944758, 2021). "Therefore, beneficial regulation of miRNAs on HIF-1α strengthens their tumor-suppressive activity, suggesting that miRNAs or their mimics may serve as anticancer agents through inhibition of tumor metastasis and multiple hypoxia-induced responses." (PMID 34277453, 2021). "These cancer patient data support the notion that the NPM1/HIF‐1α interaction also occurs in solid tumors and it is highly involved in the response of cancer cells to the hypoxic tumor microenvironment, which in turn can facilitate tumor growth and resistance to therapy." (PMID 34388291, 2021). "Additionally, inhibition of angiogenic signaling through the downregulation of the hypoxic responder HIF-1α may reduce tumor growth." (PMID 34440874, 2021). "Considering that CA4-NPs might induce severe hypoxic conditions resulting in high expression of HIF-1α in tumor tissues, which could induce the overexpression of PD-L1, herein we also used a programmed death-ligand 1 antibody (aPD-L1) to prevent immunosuppression." (PMID 33933077, 2021). "However, hypoxic conditions after VDA treatment for the tumor may upregulate HIF-1α, which further increase the level of VEGF." (PMID 35004528, 2021).
tumor (continued). "The inhibition of HIF-1α by exposure of tumor cells to MJ could induce mitochondrial passage of pyruvate, leading to activation of oxidative phosphorylation and ROS production with concomitant inhibition of GLUT-1, HK 2, LDH A, and PDK-1 axis, a lifeline of tumor metabolism." (PMID 33718176, 2021). "In order to evaluate the inhibition of HIF-1α specific Nbs to the growth of tumor cells, further analysis could be conducted to incubate under a hypoxia working station to visualize the growing state, and the inhibition efficacy of Nbs under such hypoxia conditions." (PMID 34830219, 2021). "In particular, benzimidazoles can also inhibit the expression of HIF-1α protein to inhibit the stress behavior of cancer cells under hypoxic environments, and by changing the tumor microenvironment to stimulate the host’s antitumor immunity, benzimidazoles may also exert anticancer effects." (PMID 33996598, 2021). "Besides, SK-Hep1 xenograft tumor models in nude mice further confirmed that the inhibitory effect of ASP on xenograft tumors might be exerted partly via down-regulation of HIF1α and VEGF through blocking MAPK and PI3K signaling pathways." (PMID 34093799, 2021). "Previous studies have shown that hypoxia or high HIF-1α expression could directly (ZEBI, Snail, Twist, CAV-1) or indirectly (Notch, TGF-β, integrin-linked kinase) regulate EMT and the migration and invasion of various tumour cells." (PMID 34631221, 2021). "Therefore, it will be important, in future studies, to evaluate the consequence of IRE1alpha/XBP1 axis inhibition on the cross-talk between PEL cells and cells of the tumor environment or whether IRE-XBP1 signaling inhibition may interfere with HIF1α." (PMID 33513694, 2021). "Moreover, the expression of HIF-1α of tumor tissues significantly decreased." (PMID 34930284, 2021). "However, HECTD2 knockdown suppressed RCC tumor volume and weight (vs. the HIF-1α group) (p < 0.05)." (PMID 35004677, 2021). "Although the activation of HIF-1α acts as an adaptive response to hypoxia for cells, its prolonged activation is deleterious to hypoxic cells, and overexpressed HIF-1α has been reported to be associated with tumor growth, cancer metastasis, and poor prognosis, and tumor chemotherapy resistance." (PMID 35111045, 2021). "We also show that the disruption of these mutual interactions through the targeting of HIF-1α or its regulatory pathways exerts anti-tumor effects by acting at both the leukemic cell- and SC-levels, possibly representing an appealing strategy for overcoming microenvironment-mediated tumor support." (PMID 34207596, 2021). "Therefore, suppression of HIF-1α in tumor cells presents a promising treatment strategy." (PMID 34093799, 2021). "Moreover, proanthocyanidins could inhibit the hypoxia-simulated tumor angiogenesis and cell invasion in a HIF-1α-dependent manner." (PMID 33490272, 2021). "Interestingly, PKM2 can also enhance tumor angiogenesis by activating nuclear factor-κB (NF-κB) and HIF-1α and by triggering the secretion of VEGF-A, although we did not detect any significant change in HIF-1α at any time point in either our in vivo or in vitro experiments." (PMID 33905408, 2021). "Additionally, the modulatory effect of MJ on Hsp70, which plays a pivotal role as a regulator of tumor cell survival and is downstream to HIF-1α, remains unclear." (PMID 33716751, 2021). "However, 30–40% of clinically diagnosed ccRCC lack the expression of HIF-1α, suggesting that HIF-1α may act as a tumour suppressor gene in those scenarios where its expression may be mandatory for initial development but lost as the tumour progresses." (PMID 34099013, 2021). "Thus, increased HIF-1α expression in Th2 cells within hypoxic tumor areas could prevent the usage of lipid metabolism by Th2 cells as an alternative energy pathway when glucose is missing." (PMID 34135885, 2021).